TLR4 (toll like receptor 4)
Diseases named in the same sentence as TLR4 in open-access papers (continued):
Sharing a sentence is not in itself a finding about the gene and the disease.
subarachnoid hemorrhage (36 papers, 2011 to 2025). A serious neurological disorder characterized by intracranial hemorrhage into the subarachnoid space. "Toll-like receptor 4 (TLR4) activation causes excessive production of proinflammatory mediators and an increased expression of costimulatory molecules that leads to neuroinflammation after subarachnoid hemorrhage (SAH)." (PMID 35778649, 2022). "TLR4 is up-regulated and activated in the basilar arterial wall during cerebral vasospasm after experimental subarachnoid hemorrhage in rabbits, suggesting a role for TLR4-associated signaling pathway in the pathogenesis and development of inflammation in cerebral vasospasm." (PMID 25071777, 2014). "In a rat model of subarachnoid hemorrhage, elevated expression of Panx1 channels exacerbated the inflammatory injury associated with TLR2/TLR4/NF-κB signaling." (PMID 35325354, 2022). "Toll-like receptor 4 (TLR4) has been proven to play a critical role in neuroinflammation and to represent an important therapeutic target following subarachnoid hemorrhage (SAH)." (PMID 27529233, 2016). "Progesterone treatment inhibits TLR4 signaling pathways and reduces brain edema and blood–brain barrier impairment after subarachnoid hemorrhage in rats." (PMID 23414417, 2013). "Previous study suggested that progesterone administration could inhibit TLR4/NF-κB signaling pathway in the rat brain following subarachnoid hemorrhage." (PMID 38105294, 2024). "In this regard, NaHS, has been observed to modulate inflammation by inhibiting the release of tumour necrosis factor- α (TNF-α) and reducing the expression of toll-like receptor 4 (TLR4), and NF-κB in the hippocampus of Sprague-Dawley rats subject to subarachnoid haemorrhage." (PMID 36764968, 2023). "This study aimed to investigate the molecular mechanism of how melatonin (MT) interferes with hypoxia-inducible factor 1α (HIF1A) and toll-like receptor 4 (TLR4) expression, which is implicated in the management of delayed brain injury (DBI) after subarachnoid hemorrhage (SAH)." (PMID 35170388, 2022). "Erythrocytic products, such as methemoglobin and heme, may activate Toll-like receptor 4 (TLR4) on microglia, which triggers an inflammatory cascade and damages neurons and vascular endothelial cells following subarachnoid hemorrhage." (PMID 36474712, 2022). "An upregulation of TLR4 has been observed in vascular endothelial cells in response to renal ischemia reperfusion injuries, and an increase in co-localization of TLR4 and vascular endothelial cells was observed in response to subarachnoid hemorrhages." (PMID 30159311, 2018). "For example, 17β-estradiol enhances TLR4 expression in macrophages, while progesterone depresses its expression in the brain of mice with experimental autoimmune encephalomyelitis or that of rats subjected to subarachnoid hemorrhage." (PMID 24904290, 2014). "In addition, PPARγ agonists suppress the subarachnoid hemorrhage-induced inflammatory response by inhibiting TLR4 signaling." (PMID 23414417, 2013). "It has been reported that progesterone inhibits TLR4/NF-κB signaling pathway and decrease proinflammatory cytokine production in rats following subarachnoid hemorrhage, suggesting that suppressed proinflammatory signaling may contribute to preconditioning by TLR4 activation in ICH." (PMID 23414417, 2013). "In the therapy of subarachnoid hemorrhage in rats, BMSC- exosomes can significantly reduce the levels of inflammatory proteins, such as toll-like receptor 4 (TLR4) and TNF-α." (PMID 38459276, 2025). "In experimental subarachnoid hemorrhage, resveratrol decreased early brain injury, neuroinflammation and microglia activation through inhibition of NLRP3 inflammasome activation or TLR4 pathway." (PMID 36836502, 2023). "Recently, inhibition of toll-like receptor 4 (TLR4) was found to prevent the induction of increased BBB permeability and suppress the upregulation of MMP-9 after subarachnoid hemorrhage in mice." (PMID 33487119, 2021).
subarachnoid hemorrhage (continued). "Treatment with DEX after subarachnoid haemorrhage (SAH) attenuated SAH-induced early brain injury, partially through suppression of the toll like receptor 4 (TLR4)/NF-κB pathway and the NLRP3 inflammasome." (PMID 31351473, 2019). "This study was undertaken to evaluate the effect of tamoxifen on the toll-like receptor 4 (TLR4)- and nuclear factor-κB (NF-κB)-related inflammatory signaling pathway and secondary brain injury in rats after subarachnoid hemorrhage (SAH)." (PMID 24373431, 2013). "Immunohistochemical methods and Western blot showed increased levels of TLR9 and a slight increase in TLR4 and FRP2 following both subarachnoid hemorrhage as well as the application of artificial cerebrospinal fluid over time, although the individual periods were different." (PMID 39839349, 2024). "In addition, in early brain injury after subarachnoid hemorrhage, inflammatory response mediated by Panx 1 was primarily through the TLR2/TLR4/NF-κB-mediated signaling pathway." (PMID 34475813, 2021). "Furthermore, after subarachnoid hemorrhage in mice, MMP-9 is upregulated in the brain and mediates BBB permeability in a toll-like receptor 4 (TLR4)-dependent manner." (PMID 33487119, 2021). "Subarachnoid hemorrhage (SAH) elicits destruction of neuronal cells and neurological function, which is exacerbated by neuro-inflammation in EBI, and toll-like receptor 4 (TLR4) plays an important role in inflammatory cascade via modulation microglia polarization." (PMID 31803007, 2019).
bacterial sepsis (35 papers, 2007 to 2025). "In a nonhuman primate model, hyaluronidase activity decreases neutrophil bactericidal activity by interfering with TLR2/TLR4 signaling, and a hylB mutant deficient in hyaluronidase activity was deficient in establishing fetal invasion and bacteremia." (PMID 38842305, 2024). "Two TLR4 polymorphisms, D299G and T399I, have been associated with hyporesponsiveness to LPS and increased incidence of bacterial sepsis." (PMID 36246240, 2022). "Mice with either a defective or a disrupted TLR4 fail to respond to LPS and are more susceptible to bacteremia." (PMID 29928698, 2018). "In parallel with these data, the activation of the TLR4 signaling pathway, sensitivity to TLR4 inhibitors and production of TNFα are routinely associated with LPS-induced bacterial sepsis." (PMID 28542576, 2017). "A hallmark of bacterial sepsis is the uncontrolled activation of the TLR4 pathway, which is the primary cause of the pathological features associated with this disease." (PMID 28442605, 2017). "Considering the importance of TLR4 signaling in bacterial sepsis and the remarkable pathological similarities associated with infections caused by filoviruses Ebola virus (EBOV) and Marburg virus (MARV), we assessed the ability of eritoran, a TLR4 antagonist, to protect mice against these viruses." (PMID 28442605, 2017). "In bacterial sepsis, LPS binds to Toll-like receptor 4 (TLR4), expressed mainly by immune and renal tubular epithelial cells, as well." (PMID 40563351, 2025). "In bacterial sepsis, endotoxins such as LPS bind to Toll-like receptor 4 (TLR4), thereby activating the NF-κB signaling pathway and driving the overproduction of anti-inflammatory mediators, a key contributor to immunosuppression." (PMID 40364841, 2025). "For example, TLR4 was reported to control bacterial clearance and the induction of pro-inflammatory immune response during bacterial sepsis." (PMID 34938184, 2021). "Again, this is very similar to that which occurs in bacterial sepsis, as TLR4 expression is known to be significantly elevated in the myocardium upon stimulation with LPS." (PMID 33505220, 2021). "As demonstrated in bacterial sepsis, continued TLR4 stimulation results in an overexacerbated immunological response, which ultimately elicits a more damaging than beneficial response." (PMID 28442605, 2017). "Recent studies have shown that the heart expresses TLR4 mRNA and protein, and TLR4 plays a role in myocardial dysfunction during bacterial sepsis." (PMID 19691857, 2009). "TLR4 has been shown to mediate mtDNA damage through increased oxidative stress and inducible nitric oxide synthase expression in a mouse model of bacterial sepsis." (PMID 17697385, 2007). "Bacterial sepsis involves an overwhelming and dysregulated host immune response and is characterized by high levels of bacterial lipopolysaccharide (LPS) interacting with TLR4, leading to the overexpression of inflammatory mediators." (PMID 36246240, 2022). "Therefore, parallels between LPS-driven bacterial sepsis and virus-induced cytokine storm can be drawn, with a central role for TLR4 in leading to overwhelming systemic inflammation." (PMID 36246240, 2022). "TLR4 could control bacterial clearance and induce pro-inflammatory immune response during bacterial sepsis." (PMID 34938184, 2021). "TLR4 dysregulation promoted aberrant cytokine production in bacterial sepsis." (PMID 29273011, 2017). "Although treatment of bacterial sepsis with TLR4 antagonists may be limited to selected patients, there is a large potential of development for TLR4-oriented therapeutics to target sterile or microbially-induced inflammation." (PMID 28106157, 2017). "This suggests that the NOD1 pathway might exert more selective effects on the vasculature than TLR4 during bacterial sepsis and that the capacity to pharmacologically differentiate the signalling pathways of these receptors in models of vascular inflammation may be instructive." (PMID 22870324, 2012).
bacterial sepsis (continued). "The ex vivo responsiveness of PBMCs to TLR4- and T cell-receptor activation, as measured by ELISpot quantification of both TNF-alpha and IFN-gamma respectively, differed between SARS-CoV-2 and bacterial sepsis patients." (PMID 34956225, 2021). "One likely explanation for this difference is that strain 56606v is not a highly virulent strain of L. interrogans and that TLR4−/− mice could survive with high levels of bacteremia (>2.5 × 105 leptospires per μL blood)." (PMID 28536433, 2017). "Thus, in case of a bacterial sepsis, the inflammatory response in the lung will never be induced by exclusive activation of TLR2 or TLR4 but always by costimulation of TLR9." (PMID 21547259, 2011).
type 1 diabetes (35 papers, 2012 to 2025). "With the data obtained in this study, we believe that new therapeutic strategies based on TLR4 inhibitors or prebiotics will become an essential target for treating type 1 diabetes and other diseases associated with hypercortisolism in the future." (PMID 40496562, 2025). "According to our recent findings, both the expression of IL1β inflammatory cytokine and Toll-like receptor 4-sensing microbial lipopolysaccharides were markedly induced in myenteric neurons of this particular gut segment of type 1 diabetic rats." (PMID 39457659, 2024). "In another study, HSV vectors were used to express IL-10 in a Type I diabetes rat model by reducing the expression of Toll-like receptor 4 (TLR4), which reduced macrophage activation and inhibited painful neuropathy." (PMID 39598601, 2024). "Based on the previous research on the mechanism of HMGN1 in inflammation, we have shown that HMGN1 can induce inflammatory or immune responses by triggering TLR4-dependent signaling pathways in a type 1 diabetes mice." (PMID 36691481, 2023). "It was found that streptozotocin-induced type 1 diabetes resulted in cardiac contractile dysfunction, and an increase in toll-like receptor-4 (TLR4), NLRP3, caspase-1, IL-1β, IL-6, and TNF-α expression in myocardial tissue in mice." (PMID 36320147, 2022). "In individuals with longstanding type 1 diabetes, gene expression level was increased by 47% for TLR4 (p = 2.90 × 10−2, 95% CI −0.29, −0.01) and 36% for IL6 (p = 1.30 × 10−2, 95% CI −0.18, −0.02)." (PMID 33973017, 2021). "Targeting innate immunity in NOD mice with anti-TLR4/MD2 antibodies effectively reverses type 1 diabetes by downmodulating adaptive immunity." (PMID 33690220, 2021). "More recently, studies on TLR4 activation during type 1 diabetes have indicated that other host-derived molecules are capable of regulating TLR4 function." (PMID 25101057, 2014). "In STZ-induced type 1 diabetic mice, treatment with valsartan resulted in significantly reduced Egr-1, TF and TLR-4 in aorta." (PMID 25109475, 2014). "In the present study, both 7.0% w/w and 10.5% w/w FO feeding reversed STZ-induced hepatic inflammation by downregulating LPS/TLR4/MyD88 pathways, which indicated that FO supplementation may act as an anti-inflammatory food in the treatment of type 1 diabetes." (PMID 37685162, 2023). "Following this discovery, MSRV-derived Env and other HERV-W Env proteins have been shown to interact with TLR4 to induce a pro-inflammatory response in a variety of cell-types and situations, including a potential role in the development of type I diabetes (T1D)." (PMID 36839434, 2023). "Indeed, the recent suggestion that microbiota enriched in Bacteroidetes species producing hexa‐acylated LPS with strong TLR4 agonist activity promotes endotoxin tolerance and thereby protects against type I diabetes seems contradictory." (PMID 29567797, 2018). "Further studies revealed that TLR4 is also able to bind endogenous structures, including heat shock protein 60 (Hsp60), a dominant stress protein and a putative beta cell autoantigen assumed to be involved in the pathogenesis of type 1 diabetes." (PMID 24086519, 2013). "Downregulation of Pdcd4 by miR-21 has been associated with attenuation of cytotoxic effects of oxidative stress and ischemia-reperfusion in cardiomyocytes, decreasing the proinflammatory effects of TLR4 signaling, and also preventing type 1 diabetes in rodents." (PMID 22655170, 2012). "However, there is insufficient information about the role of TLR4 in type 1 diabetes-induced vascular dysfunction of large arteries, and it is unknown whether TLR4 impacts BP under type 1 diabetes." (PMID 32694567, 2020). "Therefore, our aim was to determine the proportion of TLR4-immunoreactive (IR) myenteric neurons and TLR4 subcellular localization along the duodenum-colon axis, and, furthermore, to evaluate the expression of TLR4 in different intestinal layers and gut regions using a type 1 diabetic rat model." (PMID 36672637, 2023).
type 1 diabetes (continued). "In children with type 1 diabetes for more than 3 months, the percentage (p = 0.021) and number (p = 0.018) of CD19+ TLR4+ B cells were higher than in healthy subjects." (PMID 34830017, 2021). "In the current study, we aimed to investigate possible associations between gut related inflammatory biomarkers including LBP, CD14, TLR4, I-FABP and IL-18 and the presence of CAD and with established CHD, in patients with long-term type 1 diabetes compared to a control group." (PMID 39563343, 2024). "Furthermore, the adoptive transfer of ex vivo bone marrow cells, stimulated with TLR4 antibody, into NOD mice suppressed acute type 1 diabetes induction as well." (PMID 36110844, 2022). "In a study on acute type 1 diabetes using non-obese diabetic (NOD) mice, an agonistic TLR4 monoclonal antibody was found to have a protective effect through the induction of MDSCs." (PMID 36110844, 2022).
acute pancreatitis (34 papers, 2010 to 2025). An acute inflammatory process that leads to necrosis of the pancreatic parenchyma. "We found that mice deficient in NOD1 and TLR4 were resistant to cerulein-induced acute pancreatitis and that bowel sterilization by a broad range of antibiotics prevented the development of acute pancreatitis." (PMID 38440723, 2024). "Concentrations of LBP have been found to be significantly elevated in patients suffering from severe acute pancreatitis indicating the process of TLR4 signaling may have a role in systemic complications associated with severe acute pancreatitis." (PMID 38585277, 2024). "Animal models and a number of clinical studies have shown that HMGB1, TLR4, and NF-κB are involved in the process of intestinal mucosal injury caused by intestinal ischemia-reperfusion injury, indomethacin and acute pancreatitis, all of which play important roles." (PMID 35185593, 2021). "In a clinical study investigating the impact of two TLR4 mutations, TLR4 Asp299Gly and TLR4 Thr399Ile, a tendency of higher frequency of the mutations were found in the group of severe acute pancreatitis compared both to the group of mild acute pancreatitis and the control group." (PMID 20482799, 2010). "In addition, AA’s upregulation of TLR4 and downregulation of PPARγ may be associated with acute pancreatitis." (PMID 28424593, 2017). "Bifidobacterium and its metabolite lactic acid suppress systemic inflammation and attenuate acute pancreatitis by modulating the Toll-like receptor 4 (TLR4)/MyD88 and NLRP3/Caspase-1 signaling pathways." (PMID 41277964, 2025). "TLR4-/- mice have demonstrated significantly less neutrophil infiltration in an acute pancreatitis model." (PMID 38585277, 2024). "It has been demonstrated that TLR4 signaling contributes significantly to the inflammation of acinar cells in acute pancreatitis." (PMID 39221252, 2024). "TLR4 expression is increased on monocytes 24 hours after the onset of acute pancreatitis and reduces to normal levels after 7 days." (PMID 38585277, 2024). "TLR4 can also be activated by pancreatic elastase, which has been shown to be elevated during acute pancreatitis." (PMID 38585277, 2024). "TRAF6 has also demonstrated a protective role in the progression of acute pancreatitis in acinar cells as stimulation of TLR4 lead to increased SOCS1 and SOCS3 expression, which are responsible for the degradation of TRAF6 through polyubiquitination." (PMID 38585277, 2024). "During the induction of acute pancreatitis mice utilizing LPS, an upregulation of both TLR4 and MIF were observed in the lungs of treated mice." (PMID 38585277, 2024). "TLR4 is a pattern recognition receptor expressed on a diverse population of cells and plays a multitude of roles in the progression in acute pancreatitis." (PMID 38585277, 2024). "Within 24 hours of the beginning of acute pancreatitis, monocytes produce more TLR4, which decreases to normal levels after a week." (PMID 39221252, 2024). "During severe acute pancreatitis, TLR4 is found to be elevated in liver, kidney, and intestinal tissue following induction of pancreatitis." (PMID 38585277, 2024). "TLR4 has a demonstrated role in pancreatic inflammation and in the progression of acute pancreatitis." (PMID 38585277, 2024). "Toll-like receptor 4 (TLR4) has been identified as a potentially promising therapeutic target in acute pancreatitis (AP)." (PMID 35982604, 2022). "The HMGB1/TLR4/NF-κB pathway also participates in indomethacin- and acute pancreatitis-induced intestinal mucosal injury." (PMID 35185593, 2021). "This study is aimed at investigating the effect of HFD on acute pancreatitis (AP) and the role of TLR4-mediated necroptosis and inflammation in this disease." (PMID 31998444, 2020). "Toll-like receptor 4 (TLR4) mediates the immune response and plays a proinflammatory role in the progression of acute pancreatitis by promoting neutrophil recruitment." (PMID 33553136, 2020).